MASTL (microtubule associated serine/threonine kinase like)
Diseases named in the same sentence as MASTL in open-access papers (continued):
Sharing a sentence is not in itself a finding about the gene and the disease.
triple-negative breast carcinoma (3 papers, 2018 to 2023). An invasive breast carcinoma which is negative for expression of estrogen receptor (ER), progesterone receptor (PR), and human epidermal growth factor receptor 2 (HER2). "As a single agent, MASTL inhibitors could be used to reduce proliferation and metastasis in cancers, such as triple negative breast cancer (TNBC), where MASTL is significantly overexpressed." (PMID 30555827, 2018). "MASTL is a promising anticancer target, particularly in cancers with CIN, such as triple-negative breast cancer and metastatic prostate cancer." (PMID 38129815, 2023).
gastric cancer (2 papers, 2020). A primary or metastatic malignant neoplasm involving the stomach. "MASTL has also been linked with increased motility, invasiveness, and metastatic progression in breast and gastric cancers." (PMID 32640605, 2020). "Given the established link between MASTL and metastasis in both breast and gastric cancers, it seems likely that this role may also be kinase-independent." (PMID 32640605, 2020). "In 42.9% of gastric cancer patients, MASTL was significantly associated with cancer metastasis, tumor relapse, and poor overall survival, suggesting the potential of MASTL expression as a valuable prognostic marker and a potential therapeutic target for patients with gastric cancer." (PMID 32692487, 2020).
thyroid cancer (2 papers, 2015 to 2018). "We next performed some experiments to further corroborate the dependency of thyroid cancer cells upon Cyclin D1, MASTL and COPZ1 activity." (PMID 26431489, 2015). "Collectively, our study identified Cyclin D1, MASTL and COPZ1 as thyroid cancer cell specific vulnerabilities, suggesting that they could provide a common therapeutic target in thyroid cancer treatment." (PMID 26431489, 2015). "Thus we envisage that Cyclin D1, MASTL and COPZ1 are attractive targets for new therapeutic approaches for thyroid cancer which spare normal cells and which would thus have limited side effects." (PMID 26431489, 2015). "Importantly, knockdown of MASTL reduced viability of thyroid cancer cells without significantly affecting normal cell proliferation, suggesting that MASTL inhibitors may be relatively non-toxic." (PMID 30555827, 2018).
head and neck squamous cell carcinoma (1 paper, 2018). A squamous cell carcinoma that arises from any of the following anatomic sites: lip and oral cavity, nasal cavity, paranasal sinuses, pharynx, larynx, and salivary glands. "Previous studies have shown that knocking down MASTL in breast cancer, head and neck squamous cell carcinoma cell lines make them more susceptible to chemotherapy treatments circumventing the resistance problems." (PMID 29559668, 2018). "Upregulation of MASTL is associated with various types of cancers including breast, prostate and oral cancers that correlates with the recurrence of tumor in patients suffering from head and neck squamous cell carcinoma." (PMID 29559668, 2018).
Infertility (1 paper, 2021). "Other major DEPs, including RNASEH2C, TAPBPL, TUBB8, NFRKB, MASTL, and MYLK, have never been reported to be associated with infertility, metabolic disorders, or hormone imbalances." (PMID 34016141, 2021).
Macrothrombocytopenia (1 paper, 2025). "Variants in genes not typically linked to macrothrombocytopenia, like ADAMTS13 and MASTL, were also found." (PMID 40941697, 2025).
metastatic prostate carcinoma (1 paper, 2023). A carcinoma that arises from the prostate gland and has spread to other anatomic sites. "Furthermore, MASTL overexpression is associated with CIN in breast and metastatic prostate cancers." (PMID 38129815, 2023).
prostate carcinoma (1 paper, 2023). A carcinoma that arises from epithelial cells of the prostate gland. "Moreover, MASTL regulates CIN adaptation to targeted therapy in refractory lethal prostate cancer." (PMID 38129815, 2023). "Notably, MASTL inhibits fatal levels of CIN and promotes CIN tolerance in lethal therapy-resistant prostate cancer." (PMID 38129815, 2023).
Right ventricular cardiomyopathy (1 paper, 2018). Right ventricular dysfunction (global or regional) with functional and morphological right ventricular abnormalities, with or without left ventricular disease. "Similarly, KEGG pathway analysis identified desmosome dysfunction (arrhythmogenic right ventricular cardiomyopathy), mitogen-activated protein kinase (MAPK) signalling, and proteoglycans in cancer as significantly enriched in the UP phosphopeptides following MASTL overexpression." (PMID 29743597, 2018).
thrombosis (1 paper, 2020). "These genes included STIM1 and C4BPA, which impact platelet reactivity and/or thrombosis risk, as well as MASTL and TPM4, which influence megakaryo-thrombopoiesis." (PMID 32600345, 2020).
thyroid tumor (1 paper, 2015). A benign or malignant neoplasm affecting the thyroid gland. "Of note, our study identified MASTL as a novel mitotic machinery target in thyroid tumor, in addition to PLK1 and AURKs, both overexpressed and proposed as therapeutic targets in ATC." (PMID 26431489, 2015). "Further analysis of three selected hit genes, namely Cyclin D1, MASTL and COPZ1, showed that they represent common vulnerabilities for thyroid tumor cells, as their inhibition reduced the viability of several thyroid tumor cell lines, regardless the histotype or oncogenic lesion." (PMID 26431489, 2015). "To assess whether the survival genes confirmed in BCPAP cells are involved in such common pathways, we investigated the effect of CCND1, MASTL and COPZ1 gene silencing in a panel of thyroid tumor-derived cell lines representative of different tumor histotypes." (PMID 26431489, 2015). "Interestingly, we found that silencing of Cyclin D1, MASTL and COPZ1 inhibits the growth of several further thyroid tumor cell lines." (PMID 26431489, 2015).
uterine cancer (1 paper, 2023). Primary or metastatic malignant neoplasm involving the uterine corpus and/or the cervix. "Using DEC-Tec or other drug discovery platform, one might identify novel small-molecule inhibitors of kinase genes in uterine cancer, including TTK and MASTL, representing future work from our previous study." (PMID 37141409, 2023).
cancer (24 papers, 2015 to 2026). A tumor composed of atypical neoplastic, often pleomorphic cells that invade other tissues. "Cancer is responsible for the highest disease burden globally, and MASTL is implicated as a poor prognostic factor in several of the most lethal cancer subtypes, including breast, gastric, colon, liver, non-small-cell lung cancer (NSCLC), and ovarian." (PMID 32640605, 2020). "MASTL upregulation has now been detected in multiple cancer types and associated with aggressive clinicopathological features." (PMID 32692487, 2020). "Another activator of MRTF/SRF signaling with an arising role in cancer progression is microtubule-associated serine/threonine kinase-like (MASTL)." (PMID 33255630, 2020). "Understanding what functional impact these mutations and truncations have on MASTL function in cancer will be of interest for future research." (PMID 30555827, 2018). "Upregulation of MASTL in various cancers and its association with poor patient survival establishes it as an important drug target in cancer therapy." (PMID 29559668, 2018). "Given that cancer cells are actively proliferating with increased numbers of mitotic cells, it appears that increased MASTL in various cancers is associated with the increased mitotic activity of cancer cells." (PMID 29976159, 2018). "Interestingly, we and other groups showed MASTL upregulation in multiple types of cancer, in association with aggressive clinicopathological features." (PMID 36247015, 2022). "Importantly, MASTL has been implicated to play a substantial role in cancer progression and subsequent studies have shown that MASTL is a significant regulator of the cellular actomyosin cytoskeleton." (PMID 32640605, 2020). "Interestingly, MASTL is overexpressed in several cancers with an associated increase of chromosome instability and associated with a poorer outcome of patients." (PMID 32978522, 2020). "Moreover, MASTL upregulation was associated with recurrence after initial treatment, thereby decreasing cancer patient survival in a number of cancer types." (PMID 32692487, 2020). "Moreover, MASTL inhibition caused mitotic cell death in various cancer cells, with less damage to normal cells." (PMID 33117702, 2020). "Of note, this study revealed a cancer-associated truncated version of MASTL, referred to as MASTL450 that displays catalytic activity, not on Arpp19 or ENSA, but on novel substrates, such as high mobility group protein A1 (HMGA1), which has been linked to the metastatic progression of cancer cells." (PMID 32640605, 2020). "Moreover, a causal role for MASTL in resistance against anti-cancer therapies has been demonstrated using cell lines derived from initial and recurrent tumors of head and neck squamous cell carcinoma." (PMID 30068336, 2018). "Through the whole cell ABPPassay, the microtubule-associated serine/threonine kinase-like (MASTL),known for its involvement in mitotic control and cancer progression,was identified as specifically upregulated by HSP90." (PMID 41433248, 2026). "The role of MASTL in promoting cancer aggressiveness and therapy resistance is also well documented, including in CRC, in which we previously demonstrated that MASTL regulates CRC cell survival and CSC niches in a manner dependent on Wnt signaling." (PMID 37508547, 2023). "We also show that PYCR2 impacts the CSC population by regulating cancer cell survival in a MASTL/Wnt-signaling-dependent manner." (PMID 37508547, 2023). "Based on our finding that MASTL-ENSA regulates spindle pole integrity by regulating p-Aurora A in cancer cells, we explored the therapeutic potential of targeting the MASTL-ENSA-Aurora A pathway." (PMID 38129815, 2023). "We previously reported that MASTL regulates CRC progression by regulating cancer cell apoptosis in a manner dependent on Wnt/β-catenin signaling." (PMID 37508547, 2023).
cancer (continued). "Further studies revealed that PYCR2 regulates Wnt/β-catenin-signaling in manners dependent on the expression of MASTL and the cancer stem cell niche." (PMID 37508547, 2023). "Microtubule-associated serine/threonine kinase-like (MASTL) has emerged as a critical regulator of mitosis and as a potential oncogene in a variety of cancer types." (PMID 35732702, 2022). "In this article, we review the role of MASTL in cancer progression and the current gaps in this knowledge." (PMID 32692487, 2020). "MASTL knockdown in recurrent tumor cells resensitized their response to cancer therapy and potentiated cancer cells to cell death in chemotherapy." (PMID 32692487, 2020). "Considering its key significance in cancer progression and therapy resistance, recent years have witnessed growing interest in targeting MASTL as a therapeutic target for cancer therapy." (PMID 32692487, 2020). "MASTL is commonly overexpressed in cancer, which makes it a potential therapeutic anticancer target." (PMID 32978522, 2020). "Current studies have also demonstrated a possibility for targeting MASTL in therapy with DNA damaging agents including cisplatin, radiotherapy, and 5‐FU in several cancer types." (PMID 32692487, 2020). "Together, these data suggest that MASTL inhibition possesses strong potential for cancer therapy with small molecule inhibitors." (PMID 32692487, 2020). "Also, a key role of MASTL in oncogenesis has recently been proposed in different cancer types, however, details of the underlying mechanism/s and/or factors regulating MASTL expression/activity during cancer progression remain unclear and needs detailed molecular investigation." (PMID 32692487, 2020). "The roles of MASTL in cancer are many and various, where multiple studies have reported that silencing decreases cell proliferation, migration, and invasion, while overexpression can enhance these properties." (PMID 32640605, 2020). "Taken together, these results suggest that knockdown of MASTL can block both tumour growth and prevent the invasion and metastasis of cancer cells in vivo." (PMID 29743597, 2018). "Inhibition of MASTL as a therapeutic strategy for cancer has received growing interest in the last few years, with potential for both single agent therapy and combination with current standard of care treatments." (PMID 30555827, 2018). "It will be of great interest to determine if and how well conserved this function is in higher eukaryotes and human cells, and if this can explain how MASTL overexpression results in deregulation of the AKT/mTOR pathway in cancer." (PMID 30555827, 2018). "In current studies, we identify MASTL as a therapy target in colon tumorigenesis that appears to be highly upregulated in cancer cells, and thus promises minimal toxicity." (PMID 30068336, 2018). "Conversely, knockdown of MASTL can sensitize cancer cells to cisplatin, radiotherapy and 5-fluorouracil (5FU) in several cancer types, most likely by preventing cells from re-starting the cell cycle following damage." (PMID 30555827, 2018). "Although several recent studies indicated that MASTL inhibition reduced cancer cell proliferation, the selective nature of the antitumor mechanism of MASTL inhibition in cancer cells is poorly understood." (PMID 29976159, 2018). "By contrast, cancer cells demonstrate robust MASTL expression, especially by cells that were highly tumoroigenic and metastatic, including HCT116 and SW620 cells." (PMID 30068336, 2018). "It is clear that upregulation of MASTL and or loss of PP2A-B55 can promote CIN, cancer growth and invasion." (PMID 30555827, 2018). "Although the function of MASTL during mitosis has been deeply characterized in multiple organisms, our understanding of its relevance in human cancer is still limited." (PMID 29229993, 2018). "Recent studies suggest that MASTL expression is highly upregulated in cancer and confers resistance against chemotherapy." (PMID 30068336, 2018).
cancer (continued). "In recent years MASTL has also emerged as a novel oncogenic kinase that is upregulated in a number of cancer types, correlating with chromosome instability and poor patient survival." (PMID 30555827, 2018). "We found consistent and significant alterations in the expression of Survivin and Bcl-xL, key proteins of anti-apoptotic pathways and upregulated in cancer cells, in MASTL-silenced cells versus control cells." (PMID 30068336, 2018). "Another implication of this study is on the development of MASTL inhibitors, which should be able to delay mitotic entry after DNA damage and sensitize cancer cells to radiotherapies." (PMID 26923777, 2016). "MASTL (microtubule-associated serine/threonine kinase-like), more commonly known as Greatwall (GWL), has been proposed as a novel cancer therapy target." (PMID 27563826, 2016). "In this connection, it is intriguing that the level of MASTL differs considerably between different cancer cell lines (our unpublished data)." (PMID 26923777, 2016). "This, consequently, could induce deleterious CIN in CIN-resistant cancers, highlighting the potential of pharmacological MASTL inhibitors as therapeutic agents that induce fetal CIN in cancer." (PMID 38129815, 2023). "Taken together, these data suggest that MASTL may phosphorylate several additional substrates, providing insight into the ever-increasing biological functions and roles MASTL plays in driving cancer progression and therapy resistance." (PMID 35732702, 2022). "Collectively, these data suggest that MASTL may phosphorylate additional substrates, which likely support its expanding functional repertoire in cancer progression and therapy resistance." (PMID 35732702, 2022). "Thus, MASTL is likely to play a broad role in promoting tumor progression in various types of cancer, and the translational potential of MASTL targeting can be extended beyond OSCC." (PMID 36247015, 2022). "Many of these new potential substrates, such as tubulin and hnRNPM, may help explain the growing list of MASTL functions including how MASTL promotes cancer, EMT and chemoresistance." (PMID 35732702, 2022). "Notably, MASTL are highly expressed in multiple types of cancers, including breast, head and neck, gastric, thyroid, and colorectal cancers." (PMID 34358073, 2021). "Despite the well documented role of the MASTL in cancer progression and malignancy, its regulation remains largely unknown." (PMID 32692487, 2020). "Taken together, MASTL kinase has emerged as a novel target for cancer therapeutics, and hence development of small molecule inhibitors of MASTL may significantly improve the clinical outcomes of cancer patients." (PMID 32692487, 2020). "Although the role of MASTL has been widely studied in cancer, it remains unclear whether MASTL supports cancer progression via kinase-dependent or -independent functionalities." (PMID 32640605, 2020). "Several studies have reported that MASTL is highly expressed in a variety of human cancers." (PMID 32692487, 2020). "In order to analyze in more detail the consequences of MASTL ablation in cancer cells, we generated a conditional CRISPR/Cas9 system in which MASTL genetic knock out could be achieved in an inducible manner." (PMID 29229993, 2018). "Finally, we will explore the rationale for the future development of MASTL inhibitors as new cancer therapeutics." (PMID 30555827, 2018). "Taken together, we propose a classic two hit model for how MASTL overexpression drives cancer." (PMID 30555827, 2018). "In this review, we will explore the recent publications on the role of MASTL deregulation in cancer, the mechanisms by which MASTL may directly and indirectly promote tumorigenesis, and its potential as a therapeutic target." (PMID 30555827, 2018). "Overexpression of MASTL mRNA was observed in up to 10% of some cancer types." (PMID 29743597, 2018). "Indeed, MASTL is upregulated in different types of cancers by playing a crucial role in mitotic progression." (PMID 29559668, 2018).